SH3PXD2B (SH3 and PX domains 2B)
Diseases named in the same sentence as SH3PXD2B in open-access papers:
SH3PXD2B is named in the same sentence as 42 diseases in open-access papers, as found by Europe PMC text mining. Sharing a sentence is not in itself a finding about the gene and the disease. The quoted sentences say what the papers report.
Frank-Ter Haar syndrome (18 papers, 2011 to 2026). A syndrome defined by megalocornea, multiple skeletal anomalies, characteristic facial dysmorphism (wide fontanels, prominent forehead, hypertelorism, prominent eyes, full cheeks and micrognathia) and developmental delay. "Exome data analysis have identified an additional disease causing variant (NM_001308175.2: c.280C>G; p.R94G) in the SH3PXD2B gene in the affected individuals of family B. Variants in this gene are responsible for Frank-Ter Haar syndrome (FTHS)." (PMID 39280098, 2024). "Mutations in the Tks4 gene (SH3PXD2b) cause a rare developmental disorder called Frank-Ter Haar syndrome (FTHS), which leads to heart abnormalities, bone tissue defects, and reduced adiposity." (PMID 35955935, 2022). "The R43W mutation beside SH3PXD2B’s PIP-stop causes Frank-Ter Haar syndrome and is linked to colon cancer while a proximal E96K mutation is linked to endometrioid carcinoma." (PMID 34069055, 2021). "Homozygous mutational inactivation of Sh3pxd2b causes Frank-ter Haar syndrome (FTHS), a genetic disease that affects bone tissue as well as eye, ear, and heart functions." (PMID 30962481, 2019). "Inactivating mutations in the SH3PXD2B gene cause a rare genetic disorder known as Frank-ter-Haar syndrome (FTHS, OMIM:249420)." (PMID 31671862, 2019). "The most common underlying genetic defect in Frank-ter Haar syndrome appears to be a mutation in the SH3PXD2B gene on chromosome 5q35.1." (PMID 23140272, 2012). "Loss of function mutations in SH3PXD2B have been linked to the form of congenital glaucoma occurring in Frank-Ter Haar syndrome and nee mutant mice." (PMID 22509100, 2012). "A genetic basis for Frank-ter Haar syndrome has recently been established through homozygosity mapping studies in patients from 12 affected families, identifying homozygous mutations in the SH3PXD2B gene on chromosome 5q35.1 as the most common cause." (PMID 23140272, 2012). "Following the identification of mutations in Frank-ter Haar syndrome, it was noted that the region of homozygosity on chromosome 5 included the SH3PXD2B gene." (PMID 23140272, 2012). "Iqbal Z., Cejudo-Martin P., de Brouwer A., van der Zwaag B., Ruiz-Lozano P., Scimia M.C., Lindsey J.D., Weinreb R., Albrecht B.,Megarbane A., Alanay Y. Disruption of the podosome adaptor proteinTKS4 (SH3PXD2B) causes the skeletal dysplasia, eye, and cardiacabnormalities of Frank-Ter Haar syndrome." (PMID 38952703, 2024). "Frank-ter Haar syndrome (FTHS) is an inherited disease associated with variants of the SH3PXD2B gene, encoding for the podosomal adaptor protein known as TKS4." (PMID 41521804, 2026). "Homozygous mutations in the SH3PXD2B and MMP14 genes cause Frank-Ter Haar syndrome and Winchester syndrome, respectively, whereas MMP2 gene mutation causes Torg and MONA syndromes." (PMID 41246610, 2025). "Homozygous mutation of Sh3pxd2b can lead to the rare genetic disease Frank-ter Haar syndrome (FTHS, OMIM:249420), which affects several tissues due to the defect of Tks4." (PMID 31387265, 2019). "Sh3pxd2b null mice appear to share many of the skeletal, craniofacial, cardiac and ocular defects described in Frank-ter Haar syndrome, supporting the link between this gene and the syndrome." (PMID 23140272, 2012). "Here we describe three siblings with the Frank-ter Haar syndrome phenotype, all of whom are homozygous for a complete deletion of exon 13 of the SH3PXD2B gene." (PMID 23140272, 2012). "Mice lacking the podosome protein Tks4 (SH3PXD2B) have bone abnormalities that result in skeletal dysplasia that is associated with Frank-Ter Haar Syndrome." (PMID 22238651, 2012). "A variety of specific SH3PXD2B gene mutations have been reported in families with the Frank-ter Haar syndrome phenotype, but none so far have reported specific involvement of exon 13, the region of the gene affected in this family." (PMID 23140272, 2012).
melanoma (12 papers, 2011 to 2025). A malignant, usually aggressive tumor composed of atypical, neoplastic melanocytes. "SH3PXD2B (Tks4) is a scaffold protein that plays a critical role in the invasion and metastasis of various types of tumors as hepatocarcinoma, melanoma, and breast cancer." (PMID 35893033, 2022). "Actually, SH3PXD2B has been demonstrated to promote the intravascular and extravascular invasion and metastasis of human colon cancer, breast cancer, and melanoma cells." (PMID 33906640, 2021). "Our results extended previous observations of up-regulated SH3PXD2B expression in human melanoma and that up-regulated Tks5, another Tks adaptor protein similar to SH3PXD2B, expression has prognostic potential for human melanoma, breast cancer, glioma, lung cancer, and prostate cancer." (PMID 33906640, 2021). "However, the same study indicated that SH3PXD2B silencing inhibited the proliferation of melanoma cells in the collagen I-based three-dimensional cultures, as well as both primary and metastatic tumor growths in vivo." (PMID 33906640, 2021). "This antibody, which recognized the predicted protein of approximately 120 kD in a western blotting experiment, detected high levels of SH3PXD2B in several human tumor cell lines e.g. in HeLa, 293T, the acute B-cell leukemia line REH, the erythroleukemia cell line TF1 and the A2058 melanoma." (PMID 21886807, 2011).
glaucoma (9 papers, 2012 to 2025). Increased pressure in the eyeball due to obstruction of the outflow of aqueous humor. "More recently, in a mouse model of secondary congenital glaucoma caused by a spontaneous mutation of the SH3 and PX domains 2B (Sh3pxd2b) gene, it was shown that ooDSGCs have high susceptibility to glaucoma." (PMID 36035999, 2022). "Based on these observations, we set out to test cohorts of glaucoma patients for mutations in the SH3PXD2B to determine if the same defects that cause glaucoma in the Sh3pxd2b mutant mice are responsible for human disease." (PMID 22509100, 2012). "Recently, these investigations identified the SH3 and PX domains 2B (SH3PXD2B) gene as a potential glaucoma-causing gene." (PMID 22509100, 2012). "In summary, we previously showed that mutation of Sh3pxd2b generates a severe, congenital form of glaucoma in mice, which suggests that the human ortholog (SH3PXD2B) and interacting proteins are also good candidates for causing disease in humans." (PMID 22509100, 2012). "However, ADAM15 was shown to be a binding partner and target for the podosomal-adaptor protein SH3PXD2B that is mutated in the nee mouse model of glaucoma." (PMID 38394161, 2024). "SH3PXD2B, mutated in glaucoma-associated Frank–Ter Haar syndrome, encodes a cytoskeletal adaptor protein involved in podosome formation that is widely expressed in the eye although its primary site of action in anterior segment development remains to be determined." (PMID 27483349, 2016). "Here, we use immunohistochemistry to describe localization of the SH3PXD2B protein throughout the adult human eye and test whether sequence variants in SH3PXD2B occur in multiple other forms of glaucoma." (PMID 22509100, 2012). "The results demonstrate that SH3PXD2B is broadly expressed in many ocular tissues important to glaucoma and that the SH3PXD2B gene harbors rare variants that may be important in the pathophysiology of glaucoma." (PMID 22509100, 2012). "Thus, two independent lines of investigation have suggested that severe loss-of-function mutations in SH3PXD2B could contribute to developmental forms of glaucoma." (PMID 22509100, 2012). "From 21 glaucoma disease-associated genes with measurable expression, 2 were upregulated (MYOC and FOXE3) and five were downregulated (SH3PXD2B, NF1, SBF2, ADAMTS17, and FOXC1)." (PMID 35348588, 2022). "In this respect, mutations in FOXC1, PITX2, SH3PXD2B and LMX1B, among others, cause various ASDs and have a significantly increased risk of early onset glaucoma." (PMID 27483349, 2016). "We detected 14 instances of 11 non-synonymous SH3PXD2B coding sequence variations in our cohorts of primary congenital glaucoma, Axenfeld-Rieger syndrome, primary open angle glaucoma, and control subjects." (PMID 22509100, 2012). "Both Sh3pxd2b null and Sh3pxd2b nee mice appear to develop ocular features including corneal opacities and anterior segment dysgenesis resulting in early-onset glaucoma." (PMID 23140272, 2012). "In genetic experiments, exon sequences of SH3PXD2B from patients with primary congenital glaucoma (n=21), Axenfeld-Rieger syndrome (n=30), and primary open angle glaucoma (n=127) were compared to control subjects (n=89)." (PMID 22509100, 2012). "Analysis of mutant mouse strains and linkage analysis with human families have both demonstrated that mutations influencing the podosomal adaptor protein SH3 and PX domains 2B (SH3PXD2B) can result in a congenital form of glaucoma." (PMID 22509100, 2012). "SH3PXD2B is widely distributed in the adult human eye, including several tissues important to glaucoma pathogenesis." (PMID 22509100, 2012). "Finally, we have shown with immunohistochemistry that SH3PXD2B is expressed in tissues of the human eye that are important in the glaucoma including the trabecular meshwork, ciliary body, and retina." (PMID 22509100, 2012). "We have tested the role of SH3PXD2B in glaucoma pathogenesis." (PMID 22509100, 2012).
glaucoma (continued). "Multiple lines of evidence suggest that SH3PXD2B is relevant to human glaucoma." (PMID 22509100, 2012). "While analyses of these data were unable to establish a statistically significant link between SH3PXD2B and these eye conditions, we have demonstrated that SH3PXD2B is localized to multiple tissues relevant to glaucoma and identified changes warranting future functional studies." (PMID 22509100, 2012).
hepatocellular carcinoma (5 papers, 2018 to 2024). A malignant tumor that arises from hepatocytes. "It is found that SH3PXD2B is involved in the protein binding, cytoplasm and cell junction in hepatocellular carcinoma." (PMID 29933410, 2018).
Obesity (4 papers, 2009 to 2024). Accumulation of substantial excess body fat. "Methylation at cg00718518 (SH3PXD2B) in liver tissue biopsies has been previously associated with obesity." (PMID 32653021, 2020). "We investigated whether variants in CTNNBL1 (including rs6013029) and in three other genes (SH3PXD2B, SLIT3 and FLJ42133,) were associated with obesity." (PMID 19228371, 2009).
glioma (2 papers, 2021 to 2023). A benign or malignant brain and spinal cord tumor that arises from glial cells (astrocytes, oligodendrocytes, ependymal cells). "To further confirm these results, we evaluated the expression levels of SH3PXD2B, SH3PXD2A and EFHD2 mRNAs and encoded proteins in IDH-wt glioma cells (U87MG and T98G) overexpressing miR-1, miR-26a-1 and miR-487b, respectively." (PMID 36932446, 2023).
arthropathy (1 paper, 2024). Any disorder of the joints. "Specifically, homozygous inactivating mutations of the matrix metalloproteinase 2 (MMP2), MMP14, or SH3PXD2B genes may cause defective collagen remodeling and result in the allelic variants of MONA (multicentric osteolysis, nodulosis and arthropathy), Torg or Winchester syndrome." (PMID 38681749, 2024).
Axenfeld-Rieger syndrome (1 paper, 2012). Axenfeld-Rieger syndrome (ARS) is a generic term used to designate overlapping genetic disorders, in which the major physical condition is anterior segment dysgenesis of the eye. "As a result, we have tested the role of SH3PXD2B in Axenfeld-Rieger syndrome by testing a cohort of patients for disease-causing mutations." (PMID 22509100, 2012). "We tested cohorts of patients with primary congenital glaucoma, Axenfeld-Rieger syndrome, and POAG for SH3PXD2B defects and found several rare variants." (PMID 22509100, 2012).
BDCS) and (1 paper, 2023). "Borrone dermato-cardio-skeletal (BDCS) and Frank-Ter Haar (FTH) syndromes are autosomal-recessive disorders characterized by cutaneous, cardiovascular (with MVP), skeletal and other abnormalities owing to homozygote mutations in the SH3PXD2B gene (encoding the protein SH3 and PX domains 2B)." (PMID 36873395, 2023).
Cirrhosis (1 paper, 2021). A chronic disorder of the liver in which liver tissue becomes scarred and is partially replaced by regenerative nodules and fibrotic tissue resulting in loss of liver function. "It is possible that chronic HBV infection-related fibrosis and cirrhosis may up-regulate the expression of laminin that enhances SH3PXD2B expression, promoting HCC cell invasion and metastasis." (PMID 33906640, 2021).
Hearing impairment (1 paper, 2011). A decreased magnitude of the sensory perception of sound. "We examined the effects of a mutation in the Sh3pxd2b gene (Sh3pxd2bnee) on the progression of otitis media and hearing impairment at various developmental stages." (PMID 21818352, 2011).
otitis media (1 paper, 2011). Inflammation of the anatomical structures of the middle ear, which is most often caused by an infectious process. "The mouse model with a mutation in the Sh3pxd2b gene (Sh3pxd2bnee) mirrors craniofacial dysmorphology and otitis media in humans." (PMID 21818352, 2011).
cancer (22 papers, 2012 to 2025). A tumor composed of atypical neoplastic, often pleomorphic cells that invade other tissues. "Indeed, SH3PXD2B is critical for functional invadopodium formation, which is a key step for cancer cell invasion." (PMID 33906640, 2021). "Functionally, SH3PXD2B can recruit membrane type-1 matrix metalloproteinase (MT1-MMP) to the incomplete podosomes to activate MMP2 and MMP9, leading to matrix degradation and cancer cell invasion." (PMID 33906640, 2021). "However, there are no reports about the relationship between SH3PXD2B methylation and cancer." (PMID 29933410, 2018).
tumor (18 papers, 2011 to 2025). "Because FISH/Tks5 appeared implicated in malignancies, we assessed SH3PXD2B expression in tumor-derived cell lines." (PMID 21886807, 2011). "The levels of SH3PXD2B mRNA transcripts in HCC tissues of the TCGA database were significantly higher than that in non-tumor liver tissues (P < 0.001)." (PMID 33906640, 2021). "Next, we examined the intracellular localization of SH3PXD2B in the tumor-derived HeLa cells or in primary cells, e.g. HUVEC and monocyte-derived macrophages." (PMID 21886807, 2011). "In in vitro and ex vivo studies the murine ortologue of SH3PXD2B was shown to play an important role in the formation of functional podosomes, production of reactive oxygen species (ROS) by tumor cells and in the differentiation of white adipose tissue." (PMID 21886807, 2011). "Accordingly, such findings suggest that SH3PXD2B or Tks5 may modulate the tumor environment, perhaps by creating physical space for tumor cell growth or possessing growth factors by proteases, to promote tumor growth." (PMID 33906640, 2021). "Similarly, the levels of SH3PXD2B protein expression in HCC tissues of the Human Protein Atlas were also significantly higher than that in non-tumor liver tissues (P = 0.023)." (PMID 33906640, 2021). "Moreover, IHC characterization revealed that the SH3PXD2B protein was expressed in the cytoplasm of hepatocytes and the levels of SH3PXD2B expression in 89 HCC specimens were significantly higher than that in the paired non-tumor liver samples (P < 0.0001)." (PMID 33906640, 2021). "SH3PXD2B expression was up-regulated in HCC tissues in the TCGA and Human Protein Atlas as well as clinical samples, relative to that of non-tumor liver samples." (PMID 33906640, 2021). "Furthermore, qRT-PCR analysis of 24 pairs of fresh clinical HCC samples indicated that the relative levels of SH3PXD2B mRNA transcripts significantly increased in HCC tissues, compared with that in non-tumor liver tissues (P = 0.0048)." (PMID 33906640, 2021). "Based on its association with podosomes, it is not unexpected that we found SH3PXD2B highly expressed in multiple tumor-derived cell lines." (PMID 21886807, 2011). "Importantly, SH3PXD2B expression is not restricted to tumor-derived cell lines, as primary cells including human macrophages and human umbilical vein endothelial cells (HUVEC) also expressed the protein." (PMID 21886807, 2011).
SH3PXD2B also shares sentences with these, for which no sentence is quoted: colon cancer (12 papers); breast carcinoma (6); lung carcinoma (4); colorectal carcinoma (3); gastric cancer (3); genetic disease (3); prostate carcinoma (3); acute myeloid leukemia (2); congenital glaucoma (2); lipodystrophy (2); lung adenocarcinoma (2); skeletal dysplasia (2); Abdominal obesity (1); acute monocytic leukemia (1); ameloblastoma (1); colon adenocarcinoma (1); endometrioid carcinoma (1); liver cancer (1); lung large cell carcinoma (1); lung squamous cell carcinomas (1); metastatic cancer (1); metastatic melanoma (1); metastatic tumor (1); odontogenic keratocyst (1); primary congenital glaucoma (1); primary open angle glaucoma (1); Scheie syndrome (1); Winchester syndrome (1).